CTBP2 (C-terminal binding protein 2)
Diseases named in the same sentence as CTBP2 in open-access papers (continued):
Sharing a sentence is not in itself a finding about the gene and the disease.
leukemia (3 papers, 2014 to 2024). A malignant (clonal) hematologic disorder, involving hematopoietic stem cells and characterized by the presence of primitive or atypical myeloid or lymphoid cells in the bone marrow and the blood. "Incurable leukemias driven by the EVI1 oncoprotein can be reversed experimentally by blocking the binding to its cofactor CTBP2." (PMID 38748792, 2024). "Common leukemia-associated genes have been identified by the investigation of gene sets obtained by comparison of analysis 1 with analysis 3 [FLT3 and C-terminal binding protein 2 (CTBP2)] and analysis 2 with analysis 3 [NRAS and GATA binding protein 2 (GATA2)]." (PMID 29221109, 2017). "Taken together, through the initial screening studies in LCLs and further functional validation in leukemia cell lines, we found that the expression of three genes, CCDC88A, CTBP2, and SOCS4, were involved in HHT-induced response." (PMID 25628645, 2014). "Functional validation using siRNA knockdown in leukemia cell lines showed that knocking down CCDC88A, CTBP2, SOCS4 genes in U937 and K562 cells significantly altered HHT cytotoxicity." (PMID 25628645, 2014). "Transcription corepressor CTBP2 has been reported to directly bind acinus, which is regulated by NGF (nerve growth factor), inhibiting its stimulatory effect on cyclin A1 expression in leukemia." (PMID 25628645, 2014).
lung carcinoma (3 papers, 2018 to 2023). "However, further studies are warranted in different ethnic groups to validate the association between genetic polymorphisms of OCT4, REX1, and CTBP2 genes and the overall survival of primary lung cancer to reveal the underlying molecular mechanisms." (PMID 37563730, 2023). "HumanBase Gene Networks database analysis predicted that RIP140 bound to CTBP2 in lung cancer tissues." (PMID 35113002, 2022). "Overexpression of CtBP2 in lung cancer cells can induce the dephosphorylation of its target gene PTEN and enhance the cell proliferation ability." (PMID 30151388, 2018). "In this study, we found that rs313932 in the OCT4 gene, rs13409 in the REX1 gene, and rs6815391 in the CTBP2 gene interacted with some clinical features, suggesting that rs3130932, rs13409, and rs6815391 may be not independent risk factors for primary lung cancer." (PMID 37563730, 2023). "Therefore, this study intended to explore the potential association between SNPs of upstream REX1 of OCT4, downstream CTBP2 of OCT4 and OCT4, and the prognosis of lung cancer." (PMID 37563730, 2023).
osteosarcoma (3 papers, 2021 to 2025). A usually aggressive malignant bone-forming mesenchymal neoplasm, predominantly affecting adolescents and young adults. "Our results demonstrate that CtBP2 is an essential component of the CYR61-dependent pro-metastatic cascade in osteosarcoma cells." (PMID 40038783, 2025). "In the present study, we observed a positive correlation between CtBP2 levels in osteosarcoma cells and their motility in vitro as well as their invasiveness in vivo." (PMID 40038783, 2025). "Our in vitro experiments confirmed the role of micro-environmental conditions such as the oxygen levels in the regulation of CYR61-dependent induction of CtBP2 expression by osteosarcoma cells." (PMID 40038783, 2025). "Our findings identify for the first time that CtBP2 acts as a required critical inducing factor in the CYR61-related metastatic progression of osteosarcoma, by favoring cell migration and invasiveness." (PMID 40038783, 2025). "To investigate the role of CtBP2 in osteosarcoma cells, we established new isogenic cell lines either repressing or over-expressing CtBP2 by cell transduction with lentiviral vectors." (PMID 40038783, 2025). "CtBP2 is indeed required for pro-metastatic dissemination of osteosarcoma, by favoring cell migration and invasiveness." (PMID 40038783, 2025). "The in vitro expression level of CtBP2 and Cyr61 correlated positively in a panel of osteosarcoma cell lines." (PMID 40038783, 2025). "We confirmed a strong positive correlation (R > 0.8) between CYR61, CtBP2 and the stemness markers expression at the transcriptional levels in different osteosarcoma cell lines." (PMID 40038783, 2025). "Overall, we identified CtBP2 as a downstream transcriptional target of CYR61, and demonstrated that CtBP2 expression is required for CYR61-dependent pro-metastatic dissemination of osteosarcoma, by favoring cell migration and invasiveness." (PMID 40038783, 2025). "We next investigated by RT-qPCR the correlation between CYR61 and CtBP2 expression levels in a panel of eight human osteosarcoma cell lines." (PMID 40038783, 2025). "The present study suggests that CtBP2 may represent a potential pivotal target for therapeutic management of metastases spreading in osteosarcoma." (PMID 40038783, 2025). "Taken together, these results suggest that CtBP2 upregulation supports osteosarcoma cell migration." (PMID 40038783, 2025). "A wound healing assay confirmed that CtBP2 levels modulate osteosarcoma cell motility." (PMID 40038783, 2025). "Interestingly, osteosarcoma cells invading the surrounding normal tissue exhibited a higher signal intensity for CtBP2 as compared to cells located in a more core area (+ 79%; p = 0.0002)." (PMID 40038783, 2025). "Hence, CtBP2 is a crucial element of the CYR61-driven invasiveness of osteosarcoma cells." (PMID 40038783, 2025). "We then determined the protein levels of CtBP1, pCtBP1, CtBP2 and HIPK2 in osteosarcoma cells and biopsies." (PMID 33613771, 2021). "Similar experiments under serum depletion confirmed that CtBP2 levels did not influence osteosarcoma cell sensitivity to energetic stress conditions." (PMID 40038783, 2025). "Furthermore, a strong positive correlation was detected between CtBP2 and CYR61 gene expression in three independent cohorts of osteosarcoma samples from the R2 database (p < 0.05)." (PMID 40038783, 2025). "This confirmed that CtBP2 levels did not influence osteosarcoma cell sensitivity to redox stress conditions." (PMID 40038783, 2025). "Complementary experiments of cell culture under energetic substrate privation for 3 days indicated that CtBP2 levels did not influence the osteosarcoma cell response to glucose or glutamine depletion." (PMID 40038783, 2025). "Similar to the findings in the osteosarcoma cell lines, no significant induction was evident for the CtBP2 mRNA level in the osteosarcoma biopsies." (PMID 33613771, 2021).
osteosarcoma (continued). "The high homology of CtBP1 and CtBP2 led us to speculate that NSM00158 could also target CtBP1, and our results confirmed that NSM00158 targeted CtBP1 and inhibited the transactivation of MDR1, thereby increasing the chemosensitivity of osteosarcoma CSCs." (PMID 33391445, 2021). "The CtBP2 protein level was not changed in the osteosarcoma cells compared to hFOB1.19 cells." (PMID 33613771, 2021). "We also determined whether osteosarcoma biopsies had the similar expression patterns for CtBP1, CtBP2 and HIPK2 in 20 osteosarcoma biopsies and their adjacent noncancerous tissues." (PMID 33613771, 2021). "However, the CtBP2 mRNA level was not significantly changed in osteosarcoma cells compared to hFOB1.19 cells." (PMID 33613771, 2021).
polyposis (3 papers, 2018 to 2022). "Pharmacological inhibition and genetic ablation of Ctbp2 are therefore both associated with reduction in polyposis, diminished intestinal TIC populations, and reduction in Wnt pathway oncogenic signaling in Apcmin intestine." (PMID 30197752, 2018). "We have therefore demonstrated a critical link between polyposis, intestinal TIC’s and Ctbp2 gene dosage or activity, supporting continued efforts targeting CtBP in the treatment or prevention of Apc mutated neoplasia." (PMID 30197752, 2018). "As we have identified Ctbp2 as a key dependency for both Apcmin intestinal polyposis and TIC populations, we investigated whether CtBP chemical inhibition, which can also suppress polyposis, likewise reduced TIC populations." (PMID 30197752, 2018).
retinal degeneration (3 papers, 2017 to 2024). Degeneration of the retina. "To search for additional markers of retinal degeneration, we used C-terminal-binding protein 2 (CTBP2) to label photoreceptor and bipolar cell ribbon synapses." (PMID 39355864, 2024).
serous ovarian cancer (3 papers, 2020 to 2022). "CtBP2 had been identified as a novel oncogene in serous ovarian cancer, and overexpression of CtBP2 had been linked to abnormal proliferation and a lower survival rate." (PMID 34253710, 2021). "It was more convincible and clinical relevant that CtBP2’s genetic alternation would disrupt its function and attenuate it abnormal impact in serous ovarian cancer." (PMID 34253710, 2021). "Based on these findings, a novel potential treatment strategy, the combination of specific CtBP2 protein inhibitor and DNA-PK inhibitors, was proposed to target CtBP2 protein and DNA-PK in platinum-resistant serous ovarian cancer." (PMID 34253710, 2021). "CtBP2 inhibition is proposed as an appropriate therapeutic target for serous ovarian cancer therapy and as an effective treatment strategy for serous ovarian cancer." (PMID 34253710, 2021). "It was implied that CtBP1/2 protect against the degradation of stalled replication forks with opposite directions for the leading and lagging strands and CtBP2 appears to play a dominant protective role in serous ovarian cancer cells." (PMID 34253710, 2021). "It is proposed that CtBP1 or CtBP2 knockdown induce apoptosis in serous ovarian cancer cells, and that CtBP1/2-DKD accelerate the process of apoptosis while failing to generate stable double knockdown cells." (PMID 34253710, 2021). "A synergic effect of a specific DNA-PK inhibitor and CtBP2 KD would exist in serous ovarian cancer cells." (PMID 34253710, 2021). "It is possible that genetic alterations of CtBP2 destroy the abnormal activity of CtBP2 in serous ovarian cancer, resulting in a longer survival time for patients with the disease." (PMID 34253710, 2021). "CtBP2-related genetic alterations may destroy its abnormal activity and abolish the proliferation-promoting effect in serous ovarian cancer." (PMID 34253710, 2021). "To validate the hypothesis that disrupting CtBP2’s function may inhibit the abnormal growth of cancer cells, we utilized the TCGA via cBioportal to explore the potential correlation of CtBP1/2 genetic alterations with patient’s overall survival time in serous ovarian cancer patients." (PMID 34253710, 2021).
colorectal adenoma (2 papers, 2021 to 2023). An adenoma that arises from the colon or rectum. "CtBP2 was overexpressed in mouse and human colorectal adenomas." (PMID 33972635, 2021).
glioblastoma (2 papers, 2024 to 2025). The most malignant astrocytic tumor (WHO grade IV). "CtBP2 was found to activate the expression of SREBP target genes in glioblastoma cells, while it repressed the expression of the same set of genes in liver cells." (PMID 41226287, 2025).
Hepatic steatosis (2 papers, 2021 to 2023). Steatosis is a term used to denote lipid accumulation within hepatocytes. "Interestingly, even after 1 week of the dietary challenge, the liver-specific CtBP2-deficient mice exhibited hepatic steatosis with liver dysfunction as indicated by the elevated serum alanine aminotransferase (ALT) levels." (PMID 34728642, 2021). "Through this interaction, CtBP2 represses PPARα, which may contribute to hepatic steatosis and other metabolic inflexibilities in obese liver." (PMID 37286039, 2023).
intestinal polyposis (2 papers, 2018 to 2023). "Validating its oncogenic functions in mouse models, Ctbp2 haploinsufficiency dramatically reduced intestinal polyposis and prolonged survival in the Apcmin intestinal polyposis model and also extended survival and attenuated peritoneal metastasis in a mutant K-Ras–driven mouse PDAC model." (PMID 37707363, 2023). "Pharmacological inhibition of CtBP using HIPP profoundly reduced intestinal polyposis in Apcmin mice, similarly to haploinsufficiency of Ctbp2, and with no observable toxicity." (PMID 30197752, 2018).
neuroblastoma (2 papers, 2017 to 2020). Neuroblastoma (NB) is the most common solid, extracranial childhood tumor. "Furthermore, CTBP2 knockdown by lentiviral-mediated RNA interference resulted in inhibited cell growth, proliferation, migration, invasion, and cell cycle progression in neuroblastoma." (PMID 29147064, 2017).
non-small cell lung carcinoma (2 papers, 2020 to 2022). A group of at least three distinct histological types of lung cancer, including non-small cell squamous cell carcinoma, adenocarcinoma, and large cell carcinoma. "A study reported that CtBP2 promotes proliferation and reduces drug sensitivity in non-small cell lung cancer via the Wnt/β-catenin pathway." (PMID 35299743, 2022). "Recently, it was proved that CtBP2 reduced chemosensitivity of non-small cell lung cancer cells to cis-diamminedichloroplatinum (CDDP) via promoting the Wnt/β-catenin pathway." (PMID 35299743, 2022). "CTBP2 is overexpressed in non-small cell lung cancer and promotes tumor cell invasion and proliferation through the classic Wnt/β-catenin signaling pathway." (PMID 32993576, 2020).
pancreatic carcinoma (2 papers, 2011 to 2023). "We showed that overexpression of miR-141 and miR-200c led to reduced expression of CtBP2 and ZEB1 in human pancreatic carcinoma (PANC-1) cells." (PMID 21867514, 2011).
Tinnitus (2 papers, 2013 to 2021). Tinnitus is an auditory perception that can be described as the experience of sound, in the ear or in the head, in the absence of external acoustic stimulation. "We counted IHC ribbons from 3–5 animals per group (unexposed, no-tinnitus, tinnitus) as a correlate of the number of afferent auditory fibers using antibodies directed against CtBP2/RIBEYE in combination with a postsynaptic marker, the glutamate receptor isoform 4 (GluR4)." (PMID 23516401, 2013).
Alzheimer disease (1 paper, 2018). A progressive, neurodegenerative disease characterized by loss of function and death of nerve cells in several areas of the brain leading to loss of cognitive function such as memory and language. "PANTHER pathways analysis of differentially expressed proteins revealed overrepresentation of Wnt signaling pathway (CDH1, CSNK2A2, GNA11, CTBP2, CDH17, SMARCE1, p-value 0.02), followed by Alzheimer disease-presenilin pathway (MMP8, MMP9, MLLT4, CDH1, P-value 0.04)." (PMID 29515771, 2018).
anorexia nervosa (1 paper, 2025). A disorder most often seen in adolescent females characterized by a refusal to maintain a minimally normal body weight, an intense fear of gaining weight, a disturbance in body image, and, in postmenarcheal females, the development of amenorrhea. "The C-terminal binding protein 2 (CTBP2) gene (translational isoforms: CTBP2-L/S, RIBEYE) had been identified by a cross-trait analysis of genome-wide association studies for anorexia nervosa (AN) and body mass index (BMI)." (PMID 39511451, 2025).
autism (1 paper, 2022). Persistent deficits in social interaction and communication and interaction as well as a markedly restricted repertoire of activity and interest as well as repetitive patterns of behavior. "In DECIPHER database, a missense variant in CTBP2 is reported (c.979G > C, p.Glu327Gln), associated with an autism spectrum phenotype, cleft palate, diffuse white matter abnormalities, and severe intellectual disability." (PMID 36331689, 2022).
benign breast disease (1 paper, 2017). "Our results showed that the immunoreactivity of CtBP2 and Ki-67 was weak in the nucleus of mammary epithelial and myoepithelial cells in tissue samples from benign breast disease." (PMID 28412731, 2017).
breast tumors (1 paper, 2014). "ERalpha expression highly correlates with ZNF217 in lysates from breast tumors (n = 15), and ERalpha co-precipitates ZNF217 and its binding partner CtBP2 from nuclear extracts." (PMID 24962896, 2014).
cervical diseases (1 paper, 2020). "CTBP2 has not yet been reported in cervical diseases, but some studies have found that CTBP2 is associated with a variety of solid tumors." (PMID 32993576, 2020). "CTBP2 has not been reported to be related to cervical diseases, and its role in the HPV infection pathway is unknown." (PMID 32993576, 2020).
gastric tumor (1 paper, 2021). "For instance, new CTBP2-CTNNB1 fusion was found to drive RNA alteration in a gastric tumor sample." (PMID 34097189, 2021).
myocardial infarction (1 paper, 2025). Gross necrosis of the myocardium, as a result of interruption of the blood supply to the area, as in coronary thrombosis. "In summary, in adult mice, Ctbp2 overexpression promotes heart regeneration after myocardial infarction by stimulating cardiomyocytes to re-enter the cell cycle, thereby providing a protective effect against cardiac injury." (PMID 40140769, 2025). "In adult mice with cardiomyocyte specific Ctbp2 overexpression, following the construction of myocardial infarction, Brdu was administered via intraperitoneal injection for 7 consecutive days." (PMID 40140769, 2025). "Further investigation revealed that overexpressing Ctbp2 not only promoted the proliferation of primary neonatal mice cardiomyocytes but also enhanced cardiomyocyte proliferation following myocardial infarction in adult mice." (PMID 40140769, 2025). "Observations of the heart before and after isolation showed that Ctbp2 overexpression significantly ameliorated cardiac deformation and hypertrophy post-myocardial infarction." (PMID 40140769, 2025). "Additionally, WGA staining of heart tissue frozen sections demonstrated that Ctbp2 overexpression significantly reduced the cross-sectional area of cardiomyocytes after myocardial infarction." (PMID 40140769, 2025). "To further investigate the impact of Ctbp2 overexpression on the proliferative and regenerative capacity of adult cardiomyocytes, we constructed a mouse myocardial infarction model by ligating the left anterior descending coronary artery in mice with Ctbp2-overexpressing cardiomyocytes." (PMID 40140769, 2025).
pancreatic ductal adenocarcinoma (1 paper, 2019). An infiltrating adenocarcinoma that arises from the epithelial cells of the pancreas. "In the “CKP” mouse pancreatic ductal adenocarcinoma (PDAC) model driven by mutant K-Ras, Ctbp2 haploinsufficiency prolonged survival, abrogated peritoneal metastasis, and caused dramatic downregulation of c-Myc, a known critical dependency for TIC activity and tumor progression in PDAC." (PMID 31586042, 2019).
urothelial carcinoma (1 paper, 2020). A malignant neoplasm derived from the transitional epithelium of the urinary tract (urinary bladder, ureter, urethra, or renal pelvis). "Interestingly, some of these genes, such as ETV4, PTGES, CTBP2, FZD6, EAF2, and IKZF6, have not been implicated in urothelial carcinoma; thus, these genes are potential candidates for diagnostic, prognostic, and therapeutic biomarkers of urothelial carcinoma." (PMID 32391279, 2020).
viral disease (1 paper, 2024). "The CtBP family comprises two highly conserved proteins, CtBP1 and CtBP2, which have been shown to play critical roles in both tumorigenesis and the regulation of viral infections." (PMID 38932279, 2024). "Meanwhile, the two members of the CtBP family, CtBP1 and CtBP2, have different molecular structures and different binding targets, which ultimately means that they show different physiological activities, even in the same tumor or viral disease." (PMID 38932279, 2024).